CGAS (cyclic GMP-AMP synthase)
Diseases named in the same sentence as CGAS in open-access papers (continued):
Sharing a sentence is not in itself a finding about the gene and the disease.
tumor (continued). "Targetable FXa-PAR2 signaling promoting monocyte-platelet aggregate formation subverts tumor DNA stimulation of the cGAS-STING-IFN pathway required for T cell priming and efficient checkpoint inhibitor therapy." (PMID 40694429, 2025). "Cytosolic DNA activates the cGAS-STING pathway either within tumor cells or in phagocytic host cells that engulf tumor debris." (PMID 40981069, 2025). "DCs, as key mediators of tumor-derived DNA recognition, play a crucial role in initiating immune responses via the cGAS-STING pathway." (PMID 40052963, 2025). "ISAMn-MOF inhibits tumor growth and metastasis through activating the cGAS-STING pathway in melanoma." (PMID 40552295, 2025). "Irradiated tumor cells release dsDNA-containing microparticles, which activate the cGAS-STING/NF-κB pathway in macrophages and upregulate chemokine CCL20 to recruit γδ T cells." (PMID 41055972, 2025). "Are these differences due to tumor microenvironment-related signaling pathways like cGAS-STING also related to ferroptosis, ROS, and NETs?" (PMID 39849606, 2025). "We found that stromal VCAN-high, immunosuppressive CAF-rich CRC exhibited lower tumor cell-intrinsic cGAS–STING expression compared to stromal VCAN-low CRC." (PMID 40451897, 2025). "A study constructed an Mn-based metal–organic framework loaded with heavy building saponin I (PPI) and encapsulated with erythrocyte membranes to enhance cGAS–STING mediated anti-tumor immunity." (PMID 40486836, 2025). "Currently, approximately 10 STING agonists have entered clinical trials, showing significant promise in tumor immunotherapy through activation of the cGAS‐STING signaling pathway." (PMID 39834553, 2025). "cGAS-STING activation paradigm (Tsinghua-Harvard collaboration): Chemotherapy-induced tumor DNA release activates APC-intrinsic cGAS-STING signaling, establishing a molecular rationale for ICD-based combination strategies." (PMID 40741332, 2025). "Research has focused on improving tumor cell damage to trigger the cGAS-STING signaling pathway and activate the innate immune response." (PMID 41041344, 2025). "Studies have demonstrated that cGAS-STING pathway agonists significantly enhance the anti-tumor activity of NK cells." (PMID 41417876, 2025). "This study introduces a new approach to achieve tumor-specific cuproptosis-enhanced sono-immunotherapy through activating cGAS-STING pathway and sensitizing ICB." (PMID 41142419, 2025). "For instance, we have not fully elucidated how cholesterol precisely regulates the cGAS–STING pathway or how lovastatin influences other immune cells in the tumor microenvironment." (PMID 40355720, 2025). "SHK not only induced tumor necrosis but also interfered with DNA repair mechanisms in tumor cells, activating the cGAS-STING pathway and increasing PD-L1 expression." (PMID 41007722, 2025). "They demonstrated that tumor-derived RECQL4 inhibits the activation of the DC cGAS-STING pathway, thereby interfering with anti-tumor immune reconstitution following radiotherapy and ultimately reducing HCC sensitivity to treatment." (PMID 41438738, 2025). "Collectively, these findings highlight the strong association between the cGAS‐STING signaling pathway and both tumor immunotherapy and resistance mechanisms." (PMID 39834553, 2025). "Owing to its function, Mn2+ doping into nanoparticles for cGAS-STING-mediated tumor immunotherapy has garnered wide attention." (PMID 40033359, 2025). "In summary, researchers designed immune-activated nanoplatforms to enhance anti-tumor immune responses based on the role of Pt compounds in activating the cGAS–STING pathway." (PMID 40486836, 2025). "It increases PD-L1 expression on tumor cells but activates the cGAS/STING pathway, triggering cytokine production (e.g., CCL5, CXCL10) that recruits and activates CD8+ T cells." (PMID 39949780, 2025).
tumor (continued). "During viral replication, both viral double-stranded DNA and tumor-derived cytosolic DNA accumulate and are recognized by the DNA sensor cGAS, which catalyzes the synthesis of cyclic GMP-AMP (cGAMP) from ATP and GTP." (PMID 41451200, 2025). "Activation of cGAS/STING inflammosomes and triggering of immunogenic cell death are cellular mechanisms underlying TTFields’ anti-tumor action." (PMID 41473750, 2025). "In a study of intestinal cancer, methionine deprivation promoted the cGAS-sting-interferon pathway and inhibited tumor growth." (PMID 40018041, 2025). "On the other hand, the cGAS-STING pathway can promote tumor immune evasion under microenvironmental stress." (PMID 40567603, 2025). "On one hand, cuproptotic tumor cells can directly activate their internal cyclic GMP-AMP synthase (cGAS)/stimulator of interferon genes (STING) signaling pathway, triggering the release of inflammatory factors to initiate immune responses within the TME." (PMID 40341098, 2025). "Chronic cGAS-STING activation can cause immune suppression through PD-L1 up-regulation and a pro-inflammatory TME that promotes tumor progression." (PMID 40052963, 2025). "When the cytosolic DNA sensor cGAS recognizes tumor-derived double-stranded DNA (such as micronuclear DNA, mitochondrial DNA, or exosomal DNA), it catalyzes the synthesis of the second messenger 2’,3’-cGAMP." (PMID 41573551, 2025). "Overall, this cGAS–STING‐apoptosis axis displays potential targets that overcome tumour immune evasion." (PMID 41275427, 2025). "A pathway identified as critical for the innate immune system and anti-tumor immunity is the cyclic GMP-AMP synthase (cGAS)-stimulator of interferon genes (STING) signaling." (PMID 40321752, 2025). "Paclitaxel, doxorubicin, and cisplatin promote CD8+ T anti-tumor immunity through enhancing induction of cancer cell-autonomous type I interferon via ROS-triggered oxidized mtDNA to activate cGAS-STING in breast cancer." (PMID 40552295, 2025). "This tumor-derived DNA is subsequently recognized by the cGAS within APCs, such as DCs, located in the tumor microenvironment, thereby activating the STING pathway, leading to the production of substantial quantities of IFN-I in DCs." (PMID 41041344, 2025). "The tumor-derived cytosolic dsDNA binds cGAS, which produces the second messenger cGAMP that subsequently binds STING to stimulate the type I IFN–driven inflammatory response, including the production of T cell chemokines." (PMID 41129257, 2025). "It is likely that the PARP inhibitor-mediated activation of the cGAS/STING pathway is responsible for this CX3CL1 induction, as it has also been found in BRCA-deficient tumour cells, causing similar STING activation as PARP inhibitors." (PMID 39862711, 2025). "We found that tumor cell clusters with higher CGAS or STING1 expression exhibited stronger receptor-ligand interactions with T cells." (PMID 40735041, 2025). "A finding reveals that tumour exosomal ENPP1 hinders cGAS‐STING signalling by hydrolysis of 2′3′‐cyclic GMP‐AMP (cGAMP) in immune cells, thereby facilitating tumour immune evasion." (PMID 40032646, 2025). "MnO2-melittin nanoparticles have been engineered to effectively harness the TME, catalyzing a Fenton-like reaction to induce tumor cell death and stimulate the cGAS-STING pathway." (PMID 40083941, 2025). "The presence of DNA in the cytoplasm, resulting from genomic instability, activates DNA sensors like cGAS, leading to a type I interferon response that enhances anti-tumor immunity." (PMID 40563651, 2025). "In tumor immunity, our previous work demonstrated that the SUV39H1–UHRF1 complex promotes cGAS chromatin association and suppresses its activity through methylation." (PMID 40595456, 2025). "Studies have shown that cGAS-STING signaling activation has an important regulatory role in tumor immunity." (PMID 41246345, 2025).
tumor (continued). "The observed reduction in efficacy indicates that the anti-tumor immune response elicited by radiotherapy is dependent primarily on the activation of the cGAS–STING signaling pathway intrinsic to tumor cells." (PMID 40355720, 2025). "To investigate the role of cGAS-STING pathway in anti-tumor of BF839, we constructed B16-STING-KO cell model." (PMID 40231233, 2025). "DAMPs such as ATP attract dendritic cells and promote their maturation, while cytosolic DNA released from dying tumour cells activates the cGas-STING-type I interferon signalling pathway in dendritic cells and stromal cells." (PMID 41226343, 2025). "Lactylation at K21 of cGAS promotes tumor growth by accelerating cGAS protein degradation and suppressing interferon production through a ubiquitin-independent mechanism." (PMID 40720394, 2025). "PEG-PC7A facilitates pH-responsive drug release, ensuring site-specific activation within the tumor microenvironment while regulating immune responses through the cyclic GMP-AMP synthase (cGAS)-stimulator of interferon genes (STING) pathway." (PMID 40264674, 2025). "The following section will systematically dive deep into the characteristics of tumours, thereby providing essential context for understanding the intricate role of the cGAS–STING pathway in urologic malignancies." (PMID 41275427, 2025). "We also consider further investigation into the activation of the immune response within the tumor following CDH11 inhibition‐mediated cGAS‐STING activation." (PMID 39739317, 2025). "Silencing PinX1 gene can significantly enhance the sensitivity and anti-tumor immune effect of NSCLC to radiotherapy by activating the cGAS-STING pathway." (PMID 40166469, 2025). "DNA damage response (DDR) or exogenous insults such as chemotherapeutic drugs, ionizing radiation can induce cytosolic DNA accumulation in tumor cells 34, 35, which activates cGAS-STING and induces type I IFN and ISGs." (PMID 39816692, 2025). "Defects in the DNA damage response (DDR) not only promote tumor heterogeneity but also shape the tumor immune landscape through the generation of neoantigens, activation of the cGAS–STING pathway, and modulation of immune checkpoints." (PMID 41373427, 2025). "Based on the expression levels of CGAS or STING1 in tumor cell clusters, the samples were divided into high- and low-expression groups." (PMID 40735041, 2025). "Endoplasmic reticulum stress, NLRP3 inflammasome activation, NF-κB pathway, and IFN-I signaling downstream of STING are closely related to cGAS-STING-mediated apoptosis of tumor cells." (PMID 40052963, 2025). "It is possible that cGAS-STING–defective tumor cells can stimulate an immune response via cross-activation of cGAS-STING in the dendritic cells." (PMID 39851178, 2025). "Methionine deprivation modifies the nutrient metabolic pathway by inhibiting methylation, thereby promoting cGAS activity and tumor immunity." (PMID 41041344, 2025). "In HCC, the cGAS-STING pathway suppresses tumor progression by promoting immune cell infiltration and activation." (PMID 41438738, 2025). "Taken together, metallic nanomedicines hold significant promise in enhancing antitumor immune responses, either by directly activating innate immune pathways such as cGAS–STING or by potentiating PTT or RT-induced tumor ablation and subsequent ICD effects." (PMID 41049749, 2025). "This released dsDNA binds to cGAS, promoting IFNβ secretion and further enhancing anti‐tumor T cell immunotherapy through DCs‐T‐cell‐dependent functions." (PMID 40344511, 2025). "This tumor-derived DNA activates the cyclic GMP-AMP (cGAMP) synthase-stimulator of IFN genes (cGAS–STING) pathway, where cytosolic dsDNA binds to cGAS, leading to cGAMP production." (PMID 40342534, 2025). "An in vivo study has confirmed that the cGAS-STING pathway can inhibit HK2 to restrict tumor aerobic glycolysis and promote antitumor immunity." (PMID 41373022, 2025).
tumor (continued). "KTN1 binds PRMT1 and prevents its degradation, thereby potentiating β‐catenin signaling; suppressing the cGAS–STING pathway to sustain a “cold‐tumor” phenotype." (PMID 41256732, 2025). "For instance, K(L)-la of cGAS suppresses cGAMP production, thereby modulating antiviral immune responses and tumor progression." (PMID 40720394, 2025). "cGAS palmitoylation is prevalent in various tumor cell lines, and this modification is essential for cGAS to detect DNA and activate immunological signaling pathways." (PMID 40066091, 2025). "When macrophages phagocytose tumor-derived DNA within the tumor microenvironment, this triggers activation of the cGAS-STING signaling cascade, inducing robust type I interferon production." (PMID 41235258, 2025). "Due to the ability of the activated cGAS-STING pathway to elicit anti-tumor immunity in HCC, targeted and effective activation of this pathway within HCC tissue has become a critical research priority." (PMID 40098962, 2025). "The development of various STING agonists has garnered increasing attention with a growing understanding of the role of the cGAS-STING pathway in modulating anti-tumor immunity." (PMID 40520004, 2025). "The cGAS-STING pathway not only supports anti-tumor immunity but can also promote tumors and immune suppression in certain contexts." (PMID 40052963, 2025). "In this review, we aim to target cGAS-STING pathway for reprogramming TAMs to enhance anti-tumor immunotherapy." (PMID 40075527, 2025). "In conclusion, our study establishes that DHODH inhibition activates pyroptosis and cGAS-STING signaling to promote NK cell-mediated anti-tumor immunity." (PMID 41144149, 2025). "Mechanistically, it was demonstrated that radiotherapy triggers the release of dsDNA-containing RT-MPs from tumor cells, which activate the cGAS-STING/NF-κB signaling pathway in macrophages, leading to the upregulation of CCL20 expression." (PMID 41055972, 2025). "The present study further identifies KDM4B as a crucial demethylase that enhances cGAS activity by removing its methylation modification, thereby promoting anti-tumor immune responses." (PMID 40595456, 2025). "HMGB1, released by tumor cells upon forming complexes with genomic DNA, activates the cGAS‐STING pathway in dendritic cells to enhance anti‐tumor immunity." (PMID 41354099, 2025). "Building on this foundation, and motivated by the preclinical evidence that PARPi and radiotherapy can synergistically activate the cGAS-STING pathway to enhance anti-tumor immunity, the logical next step is the integration of radiotherapy." (PMID 41367875, 2025). "Activation of the cGAS-STING pathway has shown potential as a strategy to enhance anti-tumor immunity." (PMID 40052963, 2025). "Radiated tumor cell–released RT-MPs leads to Ccl20 upregulation in macrophages via cGAS-STING/NF-κB signaling pathway." (PMID 41055972, 2025). "Tumor cells often utilize mechanisms to evade immune detection, and the inhibition of the cGAS/STING pathway is one such strategy." (PMID 41583428, 2025). "The mineralization of MnO2 reduced the dosage of bacteria required to inhibit tumour growth by alleviating the hypoxic and immune‐suppressive environment in tumours and activating the cGAS‐STING pathway in mice." (PMID 39801378, 2025). "Generates mtROS, oxidizes mtDNA and promotes its leakage into the cytoplasm, resulting in the secretion of cGAS-STING-dependent IFN-I. Improves tumor antigen uptake, DC maturation, and CD8+ T cell cross-initiation." (PMID 41246345, 2025). "This biohybrid material is engineered to enhance tumor immunotherapy by synergistically activating the cGAS‐STING pathway." (PMID 41201063, 2025). "Meanwhile, we observed upregulation of cGAS expression in tumor cells, indicating effective uptake and targeted drug delivery of HCPT@ZIF-8-PDA-FA/FITC nanoparticles." (PMID 41050083, 2025). "Mice tumor samples RNA-seq analysis revealed that the cGAS-STING pathway was positively enriched in the BF839 group." (PMID 40231233, 2025).
tumor (continued). "We subcutaneously transplanted WT or cGAS-deficient MC38 cells into recipient mice, measured the diameters of emerging tumors, and calculated tumor volumes." (PMID 41419196, 2025). "Collectively, these findings demonstrate that KDM4B facilitates anti-tumor immunity and enhances the efficacy of immunotherapy by demethylating and activating cGAS." (PMID 40595456, 2025). "To further explore the impact of lovastatin on cGAS–STING pathway-mediated anti-tumor immunity, we used the cGAS–STING pathway inhibitor C-176 in a murine syngeneic tumor model." (PMID 40355720, 2025). "Meanwhile, Trim6; cGAS dKO cells substantially abrogated the tumor growth suppressive effect observed in Trim6 KO cells when MTC and B16F10 cells were transplanted into C57BL/6J mice." (PMID 40817248, 2025). "For instance, in non-small cell lung cancer, loss of cGAS-STING signaling leads to increased YAP/TAZ activity, promoting tumor immune evasion and progression." (PMID 40673277, 2025). "VNP can induce immunogenic cell death in tumor cells and trigger the activation of the cGAS/STING pathway, initiating downstream IFN-I and proinflammatory cytokine production, which in turn amplifies tumor immunogenicity." (PMID 41516132, 2025). "This intracellular stimulation of the cGAS-STING pathway culminates in an enhanced anti-tumor immune response." (PMID 40098962, 2025). "Radiotherapy has been reported to induce the accumulation of dsDNA in the cytosol of tumor cells, activating the intrinsic cGAS–STING pathway." (PMID 40355720, 2025). "It has strong anti-tumor immunity and enhances the effectiveness of various anti-cancer treatments; however, in specific types of cancers, the cGAS-STING pathway contributes to cancer growth and metastasis by altering the cancer microenvironment." (PMID 40786100, 2025). "With the current research, the cGAS-STING signaling pathway is also playing an increasingly important role in anti-tumor immunity." (PMID 41271618, 2025). "It plays pivotal roles in defending against pathogenic invasion, regulating anti-tumor immunity, and maintaining autoimmune homeostasis.Cyclic GMP-AMP synthase (cGAS) is a cytosolic DNA sensor, primarily distributed in the cytoplasm and nucleus." (PMID 40959140, 2025). "Chelation with Zn activates the cGAS-STING pathway to induce tumour cell death.D-pen binds to Cu generate ROS and inhibit ICAM and LOX." (PMID 40809021, 2025). "PTT-induced tumor ablation is generally accompanied by endogenous DNA damage in tumor cells, which activates the cGAS-STING pathway and initiates the downstream innate immune response." (PMID 40033359, 2025). "Using B16-STING-KO mouse melanoma cells, we confirmed that BF839 inhibits tumor growth via cGAS-STING signaling." (PMID 40231233, 2025). "This platform enables tumor-targeted delivery, Fe2+/Fe3+ -mediated ferroptosis, and Mn2+-driven cGAS-STING activation." (PMID 40846966, 2025). "Huang and colleagues also demonstrated that PRMT1 facilitates tumor immune evasion by suppressing the cGAS/STING signaling pathway via methylation-mediated cGAS inactivation." (PMID 40701777, 2025). "Beyond its classical antiviral role, cGAS-STING signaling is of importance to reshape the tumor immune microenvironment." (PMID 40849659, 2025). "Clinical studies have shown that docetaxel-based chemohormonal therapy increases tumor-infiltrating T cells by activating the cGAS/STING pathway and inducing IFN signaling." (PMID 40034825, 2025). "We found that cGAS–STING expression in tumor cells inversely correlated with stromal expression of versican (VCAN), an immunosuppressive CAF marker, in CRC tissues." (PMID 40451897, 2025). "PRMT5 inhibition enhances CPT‐11 sensitivity, inducing a PMS2‐deficient‐like state and cytosolic dsDNA release, which activates the cGAS‐STING pathway to promote anti‐tumor immunity." (PMID 40344511, 2025). "The mechanisms by which tumor cells suppress the activation of the cGAS-STING pathway induced by hypoxia to evade immunity are largely unclear." (PMID 40567603, 2025).